MGMT (O-6-methylguanine-DNA methyltransferase)
Diseases named in the same sentence as MGMT in open-access papers (continued):
Sharing a sentence is not in itself a finding about the gene and the disease.
glioblastoma (continued). "MGMT is a direct target gene of microRNAs, miR-370-3p, and an enhanced expression of miR-370-3p that occurs in glioblastomas increases the TMZ sensitivity." (PMID 33801310, 2021). "For instance, epigenetic silencing of MGMT has been used as a biomarker to predict response to temozolomide in patients with glioblastoma." (PMID 34603017, 2021). "Standard multimodal therapy is still valuable for selected patients with MGMT unmethylated glioblastoma." (PMID 34988453, 2021). "In this study we carried out a clinical validation of a quantitative assay for MGMT methylation detection by comparing a novel quantitative MSP using double-probe (dp_qMSP) with the conventional MSP in 100 FFPE glioblastoma samples." (PMID 33750464, 2021). "Several studies have shown that metformin and TMZ co-administration leads to a synergic response by glioblastoma cells, with an increase in mortality both in sensitive (with hypermethylated MGMT promoter) and in resistant cells to TMZ." (PMID 35008275, 2021). "Due to the absence of adequately standardized techniques, international harmonization of the MGMT methylation biomarker is still an unmet clinical need for the diagnosis and treatment of glioblastoma patients." (PMID 33750464, 2021). "The three established human glioblastoma, MGMT promoter unmethylated cell lines (LN18, T98G, and U118) were exposed to different lomeguatrib concentrations for 4, 6, 8, 24, or 48 h and lysates were subjected to Western Blot analysis." (PMID 34202589, 2021). "In MGMT unmethylated glioblastoma, we only observed a longer overall survival in residual CE volumes of 0–1 cm3 (427 days; 95% CI, 350–503), when compared to 1–5cm3 (299 days; 95% CI, 270–327; p = 0.006) or to >5 cm3 (200 days; 95% CI, 102–298; p = 0.003)." (PMID 32766140, 2020). "The primary reason to initiate this study was to re-evaluate the anatomic localization of MGMT methylated vs. unmethylated glioblastoma in light of the updated WHO 2016 classification era following conflicting reports on this topic." (PMID 32477929, 2020). "Patients aged 18–70 years with newly diagnosed methylated MGMT promoter glioblastoma with a Karnofsky performance status score >70 were considered for study." (PMID 32083011, 2020). "In this study, we evaluated the prognostic and predictive value of MGMT promoter methylation in patients with glioblastoma in Donostia Hospital." (PMID 33116181, 2020). "From the results obtained, it is known that the highest proportion of MGMT promoter methylation occurs in glioblastomas (51.4%)." (PMID 32047544, 2020). "A recent meta-analysis found that prolonged overall survival in glioblastoma patients was accompanied by MGMT promoter methylation in European and American populations but this was not the case in the Asian group." (PMID 32005184, 2020). "The role of MGMT promoter methylation for therapy response has been reported previously, especially for glioblastoma." (PMID 32841306, 2020). "In glioblastoma, the hypermethylation of O6-methylguanine DNA methyltransferase (MGMT) is determinant for administrating temozolomide." (PMID 32616071, 2020). "Meanwhile, miR-486-3p overexpression rendered glioblastoma cells more sensitive to TMZ through targeting MGMT." (PMID 32086739, 2020). "Frequently, glioblastoma patients develop chemotherapy resistance mainly due to increase expression of MGMT or other DNA repair enzymes." (PMID 33201894, 2020). "In light of the updated WHO 2016 classification, a molecularly homogenous glioblastoma population must be used to re-evaluate the topographical distribution of MGMT methylated vs. unmethylated glioblastoma." (PMID 32477929, 2020).
glioblastoma (continued). "A number of studies investigated the potential of ADC histogram parameters obtained by presurgical MRI for prediction of the MGMT promotor methylation status in glioblastoma, but the results concurrently remain ambiguous." (PMID 32158691, 2020). "Patients with MGMT methylated glioblastoma also had a longer overall survival with ≥30% NCE tumor resection (425 days; 95% CI, 286–564) than with <30% NCE tumor resection (190 days; 95% CI, 107–273; p = 0.001)." (PMID 32766140, 2020). "In glioblastoma, an increased MGMT promoter methylation has a predictive impact for increased pCR and therapy response to temozolomide." (PMID 32841306, 2020). "Hypermethylation of the promoter of MGMT is considered to have predictive value to respond to the alkylating agent temozolomide among patients harboring glioblastoma." (PMID 32973641, 2020). "There are limited studies about immune regulation mechanisms of lncRNA in IDH wild-type with MGMT promoter unmethylated glioblastoma." (PMID 32851059, 2020). "In this study, differentially expressed lncRNAs of the IDH wild-type with MGMT promoter unmethylated glioblastoma were analyzed, and Cox regression was used to construct a prognostic model for glioma patients." (PMID 32851059, 2020). "Glioblastoma stem cells are reported to express high levels of MGMT and P-gp, in both cases generating more resistance to temozolomide, and therefore a greater probability of tumor relapse." (PMID 33123485, 2020). "Examples of these are the silencing of MGMT in approximately 40% of glioblastomas and the downregulation of MMR genes in colon cancer." (PMID 33330091, 2020). "The combined use of KPS with MGMT promoter methylation and patient age in a recursive partitioning analysis modal can also accurately predict the prognosis of patients with glioblastomas." (PMID 31941467, 2020). "A study confirmed that Ktrans is related to the O6-methylguanine-DNA methyltransferase (MGMT) methylation status of glioblastomas and relative CBV (rCBV) can predict the isocitrate dehydrogenase 1 (IDH1) mutation statuses in astrocytomas." (PMID 32432046, 2020). "The current results indicated that XGBoost is superior to other methods for predicting MGMT genotype in patients with IDH1 wildtype glioblastomas." (PMID 32942564, 2020). "Level of promotor methylation to mRNA of O6-methylguanine DNA methyltransferase (MGMT) changed during drug treatment to glioblastoma patients." (PMID 33266010, 2020). "As MGMT gene promoter methylation and high expression are promising predictors in TMZ-treated glioblastoma patients, we further determined the MGMT status involving in the PCNSL patients." (PMID 30712191, 2020). "We identified a subset of glioblastoma patients by methylation clustering, who benefitted most from temozolomide treatment when the MGMT promoter is methylated." (PMID 32991787, 2020). "Among them, 2 lncRNAs (CPB2-AS1 and AC092171.2) were independent prognostic factors for IDH wild-type with MGMT promoter unmethylated glioblastoma." (PMID 32851059, 2020). "For visual inspection, heatmaps based on postcontrast T1-weighted and T2-weighted/FLAIR segmentations were created for all 436 patients combined, as well as frequency difference maps between MGMT methylated vs. unmethylated glioblastoma." (PMID 32477929, 2020). "On a non-gynecological cancer example, there is emerging evidence that the use of PARPis can potentiate the action of alkylating agents in glioblastoma tumors that have hypermethylation of the promoter of MGMT, coding for another DNA repair protein." (PMID 32483276, 2020). "MGMT promoter methylation status seems to be a prognostic predictor in patients with glioblastoma treated with alkylating chemotherapy, such as TMZ29." (PMID 33335215, 2020). "In fact, many studies have shown that low levels of MGMT in glioblastomas were sufficient to confer TMZ resistance, suggesting the existence of a MGMT-independent mechanism for TMZ resistance." (PMID 33335215, 2020).
glioblastoma (continued). "Routine determination of the MGMT status allows stratified treatment, thus, it should be used to select glioblastoma patients for clinical trials allowing to omit temozolomide in their treatment arm." (PMID 31968687, 2020). "This study identified a total of 318 immune-related lncRNAs in IDH wild-type with MGMT promoter unmethylated glioblastoma." (PMID 32851059, 2020). "The aim of this study was to assess the association between CE and NCE tumor resection and survival in light of MGMT promoter methylation in newly diagnosed IDH-wildtype glioblastoma." (PMID 32766140, 2020). "Clinical study indicated that patients with glioblastoma containing a methylated MGMT promoter obtained more benefits from TMZ than those who did not have a methylated MGMT promoter." (PMID 33628188, 2020). "MGMT promoter methylation status and IDH mutation can be considered to be further studied as prognostic factors for recurrent glioblastoma patients who received 125I brachytherapy treatment." (PMID 32513276, 2020). "Overexpression of miR-221/222 reduced MGMT levels in transfected human glioblastoma cell lines and increased the cells’ sensitivity to TMZ." (PMID 32354046, 2020). "Nevertheless, disease control for more than a few years is achieved in barely 15%‐20% of younger glioblastoma patients with tumors with a hypermethylated MGMT promoter only." (PMID 32991787, 2020). "Despite a large number of studies on biomarkers for glioblastoma, only one has regularly been applied for prognostic stratification in routine clinical use: Promoter methylation of the O-6-methylguanine-DNA methyltransferase (MGMT) gene in tumor tissue." (PMID 33003586, 2020). "We observed that extensive resection was more beneficial for patients with MGMT methylated IDH-wildtype glioblastoma in terms of survival." (PMID 32766140, 2020). "The aim of this study therefore, was to assess the association between CE and NCE tumor resection and survival in light of MGMT promoter methylation in a cohort of patients with newly diagnosed IDH-wildtype glioblastoma." (PMID 32766140, 2020). "We decided to use the human T98G cell line as the experimental model for further studies based on its human origin and the high expression levels of MGMT, whose gene methylation is a marker for better prognosis of glioblastoma patients." (PMID 33291321, 2020). "Gene expression data and clinical data of IDH wild-type with MGMT promoter unmethylated glioblastoma were acquired from the TCGA and CGGA databases." (PMID 32851059, 2020). "The enzyme O6-methylguanine methyltransferase (MGMT) removes O6-methylated DNA adducts, leading to the failure of chemotherapy in resistant glioblastomas." (PMID 32075134, 2020). "Methylation of the O6-methylguanine methyltransferase (MGMT) gene promoter is correlated with the effectiveness of the current standard of care in glioblastoma patients." (PMID 33029531, 2020). "TMZ is most effective in glioblastomas with hypermethylated promotor of the O6-methylguanine-DNA methyltransferase (MGMT)." (PMID 32101575, 2020). "It was commonly accepted that glioblastomas with IDH mutation and MGMT methylation harbors the best survival." (PMID 33247700, 2020). "Glioblastomas grow very rapidly and frequently develop resistance to treatment by increasing the expression of DNA repair enzymes such as O-6-Methylguanine-DNA Methyltransferase (MGMT), thus explaining in part the very poor prognosis." (PMID 33201894, 2020). "The utility of O6-methylguanine-DNA methyltransferase (MGMT) gene promoter methylation status as a prognostic marker in patients with glioblastoma (GBM) has been established." (PMID 33203454, 2020). "18F-Fluoro-ethyl-tyrosine (FET) has been shown to detect recurrence in previously treated glioblastomas and is influenced by MGMT promoter methylation status." (PMID 33072586, 2020).
glioblastoma (continued). "A recent study investigated the impact of maximal CE resection and MGMT promoter methylation status in a homogenous IDH-wildtype glioblastoma population (n = 175) and showed that both were significantly associated with longer overall survival." (PMID 32766140, 2020). "A total of 5 normal brain tissue expression samples and 66 IDH wild-type with MGMT promoter unmethylated glioblastoma samples were included in the TCGA database." (PMID 32851059, 2020). "Research has shown that promoter hypermethylation of the MGMT gene can be a predictor in glioblastoma multiform (GBM)." (PMID 33014773, 2020). "The status of DNA methylation using O6-methylguanine-DNA-methyltransferase (MGMT) promoter methylation status and the tumor’s copy number variation profile can be used to classify glioblastoma in various subgroups." (PMID 33575207, 2020). "In fact, hypermethylation of the MGMT promoter, which leads to decreased MGMT expression correlates with long-term survival of glioblastoma patients." (PMID 33201894, 2020). "Korfiatis and colleagues predicted the MGMT promoter methylation status in patients with glioblastoma with a sensitivity of 80% and a specificity of 81% using a four-parameter model based on T2-weighted MRI." (PMID 32394100, 2020). "Since then, numerous trials have demonstrated the prognostic effect of MGMT status on survival in patients with newly diagnosed glioblastoma." (PMID 32083011, 2020). "In this study, a deep learning pipeline is designed for automatic prediction of MGMT status in 87 glioblastoma patients with contrast-enhanced T1W images and 66 with fluid-attenuated inversion recovery(FLAIR) images." (PMID 33029531, 2020). "Patients with glioblastoma (GBM) containing a methylated MGMT promoter can benefited from TMZ therapy." (PMID 32373523, 2020). "Current guidelines recommend reflex testing for methylation of the promoter region of O6-Methylguanine-DNA methyltransferase (MGMT) in glioblastoma cases." (PMID 32640746, 2020). "The TMZ-resistant cells showed decreased basal levels of γ-H2AX, which is in agreement with the acquisition of TMZ resistance in glioblastoma that is due to an increase in the levels of DNA repair enzymes such as MGMT." (PMID 33201894, 2020). "miR-198 can improve the chemosensitivity of temozolomide in glioblastoma through targeting O6-methylguanine-DNA methyltransferase (MGMT)." (PMID 33336045, 2020). "Still, to exclude any potential influence of factors with a known association with survival measures in glioblastoma, we investigated the impact of age, patient performance status (ECOG), MGMT methylation status and extent-of-resection." (PMID 31969991, 2020). "Only 9 out of 16 HGG patients exhibited MGMT methylation: subjects 1, 5, 6, 10, 13, 19, 20, 21, 22 (all histologically confirmed glioblastoma)." (PMID 33373375, 2020). "This combination is now being evaluated in a Phase III trial in MGMT-methylated newly diagnosed glioblastoma patients with adjuvant temozolomide, with results expected soon." (PMID 33614476, 2020). "In contrast with these reports, we observed a superior PFS of 6.1 months and 6m-PFS of 52.6% for the 19 recurrent glioblastoma with unmethylated MGMT." (PMID 33634023, 2020). "Discrepancy between MGMT IHC and methylation-specific PCR results has been often reported in glioblastomas and pancreatic NETs, which is also consistent with our present results." (PMID 33287738, 2020). "MGMT promoter methylation is a prognostic factor for glioblastoma patients and has a significant correlation with worse survival rates (16.9 months vs. 12.7 months)." (PMID 33102518, 2020). "In summary, this study suggest that Allicin can increase the expression of miR-486-3p in glioblastoma, and miR-486-3p inhibits protein translation of MGMT, which reverses TMZ resistance and promotes glioblastoma apoptosis in TMZ environment." (PMID 32086739, 2020).
glioblastoma (continued). "In the second study, the addition of PD-L1 inhibitor durvalumab to SOC resulted in a modest increase of OS for patients with newly diagnosed MGMT-unmethylated glioblastoma (durvalumab 15.1 mo vs. historical controls 12.7 mo)." (PMID 32235752, 2020). "The purpose of this study is to analyze immune-related lncRNA molecules of IDH wild-type and MGMT promoter unmethylated glioblastoma and screen out prognostic factors, providing new potential targets for glioblastoma immunology research." (PMID 32851059, 2020). "Kaplan Meier estimates showed that extensive surgery was more beneficial for patients with MGMT methylated glioblastoma." (PMID 32766140, 2020). "High MGMT expressing T98G glioblastoma cells were treated with varying concentrations of Temozolomide (0, 0.2, 0.4." (PMID 32029822, 2020). "Our group previously demonstrated that mifepristone enhances the temozolomide-induced decrease in orthotopic glioblastoma tumors by increasing apoptosis and reducing levels of MGMT (thus impeding repair of DNA damage)." (PMID 33123485, 2020). "The counterpart of this trial, CheckMate 548 (NCT02667587), in which similar treatments were tested in MGMT-methylated glioblastoma patients (a phase II trial with n = ~160 per arm), showed no increase in progression-free survival (PFS)." (PMID 32235752, 2020). "Although the addition of temozolomide has modest overall survival benefit in patients with methylated MGMT promoter, it confers little benefit in the 60% of glioblastoma patients with unmethylated MGMT promoter." (PMID 32631383, 2020). "Correlation between MGMT promoter methylation and overall survival has been studied intensively in patients with both glioblastoma and neuroendocrine neoplasm." (PMID 32132978, 2020). "In glioblastoma multiforme, MGMT methylation status is a predictive biomarker for increased response to temozolomide therapy." (PMID 32841306, 2020). "The CeTeg/NOA‐09 trial was a very recently published phase III study of 141 newly diagnosed patients with MGMT‐methylated glioblastoma randomized to receive standard therapy with concurrent and adjuvant TMZ vs experimental therapy with CCNU/TMZ." (PMID 31701682, 2020). "MGMT promoter hypermethylation is currently the only known biomarker for TMZ response in glioblastoma patients." (PMID 32753598, 2020). "Pre-operative FLAIR-T2 hyperintensity area and volumes provided, independently of the measurement method, the optimal neuroimaging features predicting OS in primary glioblastoma patients, followed by age ≥ 65 years and MGMT methylation." (PMID 32984040, 2020). "Some researchers have found that cytotoxic drug withaferin A, which is involved in oxidative stress, can increase the sensitivity of glioblastoma to TMZ treatment by reducing MGMT expression and activating apoptosis induced by Akt/mTOR signaling pathway." (PMID 32086739, 2020). "Hypomethylation of DDR genes and TERT promoter mutations is associated with worse tumor prognosis, dependent on the methylation cluster and MGMT promoter methylation status in IDH wild‐type glioblastoma." (PMID 32991787, 2020). "A continuous search for a reliable molecular marker establishes the methylation status of the O6-methylguanine-DNA methyltransferase (MGMT) gene promoter as a key prognostic factor in primary glioblastoma." (PMID 30717206, 2019). "Other tests, such as the Therascreen MGMT Pyro kit for glioblastoma, can be used in the DNA obtained from blood and FFPE tissues." (PMID 31316555, 2019). "Temozolomide sensitivity in glioblastoma patients correlates with the expression and promoter methylation status of O-6-methylguanine-DNA methyltransferase (MGMT), an enzyme that counteracts temozolomide-induced DNA damage." (PMID 31810230, 2019).